IL9R (interleukin 9 receptor )
Diseases named in the same sentence as IL9R in open-access papers (continued):
Sharing a sentence is not in itself a finding about the gene and the disease.
tumor (22 papers, 2016 to 2025). "IL-9R-deficient tumor-bearing mice exhibited lower serum IL-6 level than WT mice." (PMID 35778404, 2022). "Because the IL-9/IL-9R axis is important for reducing lipid peroxidation and ferroptosis in Tc9 cells in vitro, we investigated whether IL-9 or IL-9R deficiency could affect the Tc9 cells’ ability to persist and control tumor growth in vivo." (PMID 35192544, 2022). "Conversely, IL-9 can support tumor growth in IL-9R-expressing malignancies, including lymphomas, lung cancer and pancreatic cancer." (PMID 41030439, 2025). "IL-9 can also act directly on tumor cells expressing IL-9R, such as squamous cancer (SqC) cells and cervical cancer, to directly kill these tumor cells." (PMID 36936961, 2023). "IL-9 has opposing effects on IL-9R-positive tumor cells: from cytostatic and cytotoxic effects to promoting tumor cell growth and migration." (PMID 37189417, 2023). "Flow cytometry analysis clearly showed an upregulation of IL-9R expression in the tumour tissue of wild-type and IL-9 knockout mice as compared with control tissue lacking tumours." (PMID 35793807, 2022). "Lung macrophage populations demonstrated a similar pattern as the results from i.v. injection tumor models: increased AM and decreased CD11c+ and CD11c− IM in Il9r−/− mice." (PMID 35778404, 2022). "We sorted lung AMs, CD11c+ and CD11c− IMs from WT Boy/J (CD45.1+) tumor bearing mice and then transferred them to Il9r−/− mice (CD45.2+) 4 days after tumor cell injection." (PMID 35778404, 2022). "Compared to control mice, Il9fl/fl CD4-Cre+ mice showed less tumor growth and decreased IM populations, similar to the pattern observed in Il9r−/− mice." (PMID 35778404, 2022). "In each of the tumor models, Il9r−/− mice also showed significantly lower arginase activity than WT mice, indicating differential expression is related to function." (PMID 35778404, 2022). "Immunofluorescence staining for IL-9R confirmed expression on epithelial cells of tumour tissue in wild-type mice." (PMID 35793807, 2022). "In fact, we noted here that IL-9 controls tumor cell growth in NSCLC via direct effects on IL-9R expressing cancer cells." (PMID 35514957, 2022). "While IL-9 alone was not sufficient to induce tumor migration, macrophages from both WT and Il9r−/− mice promoted tumor migration to a similar extent." (PMID 35778404, 2022). "As these findings suggested the possibility that IL-9 induces IL-9R expression in intestinal epithelial cells, we next determined the functional effects of IL-9 signalling on IL-9R expression by in vitro studies using tumour organoids." (PMID 35793807, 2022). "To understand how IL-9 signaling affects the transcriptional landscape of lung macrophages, we compared the gene expression of WT and Il9r−/− macrophages from intact lungs of tumor-bearing mice." (PMID 35778404, 2022). "Compared with macrophages within normal lung tissue, macrophages located in the tumor site expressed dramatically more IL-9R." (PMID 35778404, 2022). "The fact that Arg1-expressing macrophages can rescue tumor growth in Il9r−/− mice indicates Arg1 is a critical effector in IL-9-macrophage mediated tumor growth." (PMID 35778404, 2022). "Here, the authors show that IL-9 promotes the expansion of pulmonary macrophages and that targeting the IL-9R/arginase 1 axis restricts tumor growth, thus identifying this cytokine pathway as a potential therapeutic target." (PMID 35778404, 2022). "Mice that received WT macrophages showed more tumor growth than mice that received Il9r−/− macrophages." (PMID 35778404, 2022). "To explore if the regulatory pattern of IL-9 on macrophages is also consistent in other tumor environments, we also assessed IL-9R in a B16 s.c. model." (PMID 35778404, 2022). "IL-9R−/− mice show increased tumor growth, while, on the other hand, injection of recombinant mouse IL-9 into melanoma-bearing mice inhibits tumor growth." (PMID 34944921, 2021).
tumor (continued). "TH9-derived IL-9 leads to upregulation of p21 and TRAIL, thus inducing tumor cell cycle arrest and apoptosis upon activation of IL-9R." (PMID 27832300, 2017). "Malignant DLBCL cells in tissue sections were confirmed by pathologists, and IL-9R was located on the surface of these tumor cells." (PMID 27364124, 2016). "In our previous study, immunohistochemical analysis showed that the IL-9R protein was located on the membrane of tumor cells within DLBCL tissues." (PMID 27364124, 2016). "Currently, the role of tumor-specific IL-9R expression on Th9-mediated anti-tumor immunity in vivo remains unclear." (PMID 41030439, 2025). "These dual roles underscore the importance of tumor-intrinsic IL-9R expression and the tumor microenvironment in determining whether IL-9 promotes or inhibits tumor growth." (PMID 41030439, 2025). "T cells expressing a chimeric receptor containing the extracellular domain of IL-2R fused with the intracellular domain of IL-9R acquire features of effector T cells and show anti-tumor activity when adoptively transferred in syngeneic mouse models of melanoma and pancreatic cancer." (PMID 39281678, 2024). "Moreover, neutralizing anti-IL-9 or anti-IL-9R antibodies significantly inhibit tumor growth in mouse models of lymphoma." (PMID 39281678, 2024). "However, IL-9R knockdown in CMT167 cells abrogated the IL-9-driven tumor growth inhibition and enhanced T-cell infiltration." (PMID 37189417, 2023). "Arg1fl/flLysM-Cre− IMs, but not Arg1fl/flLysM-Cre+ IMs, rescued the loss of tumor growth in Il9r−/− mice." (PMID 35778404, 2022). "IL-9 target cells in NSCLC consisted of IL-9R+ tumor cells and tumor-infiltrating lymphocytes." (PMID 35514957, 2022). "As expected, tumor-infiltrating Il9–/– or Il9r–/– Tc9 cells had higher lipid peroxidation and cellular iron levels, and lower mitochondrial activity than WT Tc9 cells, indicating that IL-9– or IL-9 signaling–deficient Tc9 cells undergo enhanced ferroptosis in the TME." (PMID 35192544, 2022). "Although the precise reasons for these differences remain currently unclear, they may be related to the specific microenvironment provided by lung TILs in NSCLC or to the question whether the targeted tumor cell type expresses the IL-9R." (PMID 35514957, 2022). "Therefore, by repurposing IL-9R signalling using a chimeric orthogonal cytokine receptor, T cells gain new functions, and this results in improved anti-tumour activity for hard-to-treat solid tumours." (PMID 35676488, 2022). "Similar to tumor growth in the B16 i.v injection model, the Il9r−/− mice showed less tumor growth." (PMID 35778404, 2022). "Moreover, they showed that neutralizing anti-IL-9 or anti-IL-9R antibodies significantly inhibit tumor growth in mouse models of lymphoma." (PMID 34944921, 2021). "Additionally, IL-9R−/− mice showed increased tumor growth, and the injection of rmIL-9 into melanoma-bearing mice inhibited tumor growth." (PMID 32228589, 2020). "Specifically, although in a few cases, IL9R is only expressed in the tumor cells." (PMID 33329510, 2020). "In addition, melanoma tumor growth is accelerated in IL-9R−/− mice, and treatment with rIL-9 inhibited this growth." (PMID 27589682, 2016). "Similarly, Il9r(−/−) mice displayed accelerated tumor growth." (PMID 41148223, 2025). "To explore whether the macrophages themselves lead to altered tumor growth between WT and Il9r−/− mice, or whether the crosstalk between the microenvironment and the lung macrophages were the major driver, we employed a lung macrophage adoptive transfer experiment in the tumor model." (PMID 35778404, 2022). "Therefore, higher levels of IL9R might contribute to anti-tumor effects through cytotoxic effector T cells and a shifting towards a favorable ICI response." (PMID 36551692, 2022). "However, mostly, IL9R was not only detected in tumor cells but also infiltrated lymphocytes." (PMID 33329510, 2020).
tumor (continued). "However, IL-9R expression is increased in EL-4 cells, indicating an additional effect of IL-9 on tumor cells; evaluation of IL-9R expression may therefore be critical for IL-9 anti-tumor therapy." (PMID 27589682, 2016). "By contrast, these tumours lack the typical markers for GATA3+ PTCL‐NOS such as Il2ra, il9r, and Gata3 itself." (PMID 35895495, 2022). "Additionally, they could be due to certain differences in the IL-9R expression on tumour cells." (PMID 35793807, 2022). "To determine whether this concept is also relevant for tumor cells and TILs in NSCLC patients, we next assessed the distribution of IL-9R in patient samples." (PMID 35514957, 2022). "In contrast, mice lacking mast cells, which express moderate levels of IL-9 in INFER mice, have increased tumor growth and did not have the same changes in macrophage populations observed when IL-9 or IL-9R are lost." (PMID 35778404, 2022). "While it is possible AMs contribute to the IL-9-dependent tumor promoting phenotype in early tumor development, we did not observe significant changes of AM numbers comparing WT and Il9r−/− mice." (PMID 35778404, 2022). "To assess the role of IL-9 in the antitumor effects of FasL-TH9, we intravenously or subcutaneously challenged Il9r−/− mice with B16F10-OVA tumor cells and found that neither FasL-TH9 nor cTH9 enhanced antitumor immunity." (PMID 31266950, 2019). "We observed an induction of IL-9 production by tumor infiltrating lymphocytes (TIL) and a subset of FoxP3+ regulatory T cells in the tumoral region of NSCLC patients and identified tumor infiltrating T cells, FoxP3+ Treg cells and tumor cells as IL-9R expressing target cells for IL-9 signaling." (PMID 35514957, 2022). "Interestingly, TAMs in the s.c. tumor model did not express IL-9R compared to isotype control staining sample." (PMID 35778404, 2022). "Interestingly, the TAMs in the s.c.B16 tumor do not express IL-9R, which suggests the ability of IL-9 to regulate macrophages could be organ-specific or dependent on the local microenvironment." (PMID 35778404, 2022). "Strikingly, YFP+ (i.e. Arg1+) macrophages successfully recused tumor growth in Il9r−/− mice, while YFP- macrophages did not promote tumor growth." (PMID 35778404, 2022). "To elucidate the role of IL-9 in the antitumor effects of these cells, we subcutaneously challenged Il9r−/− mice with B16F10-OVA tumor cells and found that neither FasL + p38i-TH9 nor FasL-TH9 could inhibit tumor progression." (PMID 31266950, 2019).
cancer (6 papers, 2020 to 2024). A tumor composed of atypical neoplastic, often pleomorphic cells that invade other tissues. "Based on these findings, we further explored the therapeutic efficacy of targeting IL-9R signaling in lung macrophages for cancer therapy." (PMID 35778404, 2022). "Gene set enrichment analysis between WT and Il9r−/− CD11c+ or CD11c− IMs identified changes in reactive oxygen species pathways and cancer module pathways." (PMID 35778404, 2022). "Cancer cells modulate the expression and secretion of several anti-proliferative molecules on DBMSCs, including, CD40LG, CXCL9, IL9R, IL-15, TNFSF13B, IL-9, IL-17, and CXCL1." (PMID 39768220, 2024). "We also revealed six oncogenes that have been validated to be related to the poor prognosis of patients with cancer: CTSE, CALM1, PHGDH, IL9R, and CD96." (PMID 35433683, 2022).
infection (5 papers, 2017 to 2025). The state of being infected such as from the introduction of a foreign agent such as serum, vaccine, antigenic substance or organism. "As compared to C57BL/6, Il9R−/− mice showed a reduced inflammation in the initial phase of infection, but an increased susceptibility in a later phase, as indicated by fungal burden, inflammatory cell recruitment in the vaginal fluids and mucosa and IL-1β production." (PMID 30515173, 2018). "This turned out to be the case as Il1Ra was down-regulated in Il9R−/− mice at 14 days post-infection." (PMID 30515173, 2018). "IL-9R-deficient mice on both, BALB/c and C57BL/6 genetic background displayed (i) increased and prolonged parasite burden in the small intestine; (ii) reduced early degranulation of mucosal mast cells; (iii) reduced intestinal IL-13 expression and (iv) complete protection against a second infection." (PMID 29872093, 2018). "The expression of Il9 increased early and was observed throughout the infection in C57BL/6 mice, but was unaffected in Il9R−/− mice, a finding suggesting that IL-9 expression is IL-9R-dependent." (PMID 30515173, 2018). "Conversely, in Il9R−/− mice, the IL-22/NLRC4 axis was not only maximally induced but also maintained throughout the infection." (PMID 30515173, 2018). "To test the quality of the adaptive immune response that was initiated in the absence of IL-9R in a more stringent approach, we measured the immune-mediated protection against a second infection." (PMID 29872093, 2018). "Although the absence of IL-9R-mediated signalling modulated T and B cell responses during infection to some extent, functional IL-9R was not essential for the establishment of protective immune memory against a second S. ratti infection." (PMID 29872093, 2018). "Peak production of IL-9 was also observed in Rag1−/−, and less in Rag1−/−/Il9R−/−, mice early but not late in infection, a finding suggesting that early IL-9 production is IL-9R-dependent and late is T-cell-dependent." (PMID 28090087, 2017). "Importantly, our results indicate that the effects of 4-1BB stimulation are dependent on interleukin (IL)-9R signaling in B cells but independent of parasite load during primary infection." (PMID 40215168, 2025). "We provide evidence that this delayed activation of IL-9R−/− mast cells did not reflect intrinsic functional defects independent of the infection context because WT and IL-9R−/− mast cells responded equally well to FcR-mediated stimulation with model antigens or S. ratti-derived antigens in vitro." (PMID 29872093, 2018).
IL9R also shares sentences with these, for which no sentence is quoted: leukemia (2 papers); lung disease (2); acute pancreatitis (1); acute T cell leukemia (1); adenocarcinoma (1); atopic dermatitis (1); cutaneous T cell lymphoma (1); dilated cardiomyopathy (1); mantle cell lymphoma (1); megakaryoblastic leukemia (1); ovarian carcinoma (1); periodontitis (1); renal carcinoma (1); schizophrenia (1); Stroke (1); T-cell leukemia (1).